CALHM3 (calcium homeostasis modulator 3)
Description:
Pore-forming subunit of gustatory voltage-gated ion channels required for sensory perception of sweet, bitter and umami tastes. With CALHM1 forms a fast-activating voltage-gated ATP-release channel in type II taste bud cells, ATP acting as a neurotransmitter to activate afferent neural gustatory pathways. Acts both as a voltage-gated and calcium-activated ion channel: mediates neuronal excitability in response to membrane depolarization and low extracellular Ca(2+) concentration. Has poor ion selectivity and forms a wide pore (around 14 Angstroms) that mediates permeation of small ions including Ca(2+), Na(+), K(+) and Cl(-), as well as larger ions such as ATP(4-).
Synonyms: FAM26A; bA225H22.7
Tractability: Antibody: UniProt places it where antibodies can reach, with medium confidence; UniProt predicts a signal peptide or a membrane-spanning region; its Gene Ontology location is reachable by antibodies, with medium confidence.
Gene: Protein-coding gene on chromosome 10 (103,472,804 to 103,479,240, reverse strand). Ensembl gene ENSG00000183128.
Subcellular location: Basolateral cell membrane
Pathways (Reactome):
Sensory Perception: Sensory perception of salty taste; Sensory perception of sweet, bitter, and umami (glutamate) taste
Gene Ontology:
Molecular function: protein binding; monoatomic cation channel activity; voltage-gated monoatomic ion channel activity; voltage-gated channel activity
Biological process: ATP transport; protein heterooligomerization; sensory perception of taste; ATP export; monoatomic cation transmembrane transport; monoatomic ion transmembrane transport; transmembrane transport
Cellular component: basolateral plasma membrane; plasma membrane
Genetic constraint (gnomAD): Loss-of-function variants: 9 observed, 14.28 expected, observed/expected ratio (o/e) 0.63, 90% interval 0.38 to 1.1. The upper end of that interval is the gene's LOEUF score, 1.1, which puts it in group 4 of 6, group 1 being the genes least tolerant of losing a copy. Missense variants: 433 observed, 401.16 expected, observed/expected ratio (o/e) 1.08, 90% interval 1 to 1.17. Synonymous variants: 198 observed, 184.66 expected, observed/expected ratio (o/e) 1.07, 90% interval 0.95 to 1.21.
Homologues: Orthologues: chimpanzee CALHM3 (99% identical), macaque CALHM3 (94% identical), pig CALHM3 (91% identical), dog CALHM3 (91% identical), rat Calhm3 (85% identical), mouse Calhm3 (85% identical), guinea pig CALHM3 (83% identical), tropical clawed frog calhm3 (57% identical), rabbit CALHM3 (56% identical), zebrafish calhm3 (48% identical), Caenorhabditis elegans clhm-1 (20% identical). Paralogues in human: CALHM1 (43% identical), CALHM2 (26% identical), CALHM4 (20% identical), CALHM6 (20% identical), CALHM5 (18% identical).
Diseases named in the same sentence as CALHM3 in open-access papers:
CALHM3 is named in the same sentence as 2 diseases in open-access papers, as found by Europe PMC text mining. Sharing a sentence is not in itself a finding about the gene and the disease.
CALHM3 shares sentences with these, for which no sentence is quoted: Alzheimer disease (1 paper); schizophrenia (1).